RNU6-432P (RNA, U6 small nuclear 432, pseudogene)
Gene: Small nuclear RNA gene on chromosome 9 (110,903,337 to 110,903,445, forward strand). Ensembl gene ENSG00000206923.
Homologues: Orthologues: chimpanzee U6 (97% identical), macaque U6 (92% identical), guinea pig U6 (79% identical), rabbit U6 (73% identical), pig U6 (71% identical), mouse Gm25828 (54% identical). Paralogues in human: RNU6-15P (83% identical), RNU6-1042P (83% identical), RNU6-125P (83% identical), RNU6-25P (83% identical), RNU6-26P (83% identical), RNU6-33P (83% identical), RNU6-38P (83% identical), RNU6-41P (83% identical), RNU6-468P (83% identical), RNU6-574P (83% identical), RNU6-761P (83% identical), RNU6-1 (82% identical), and 1286 more.